MYCN (MYCN proto-oncogene, bHLH transcription factor)
Diseases named in the same sentence as MYCN in open-access papers (continued):
Sharing a sentence is not in itself a finding about the gene and the disease.
neuroblastoma (continued). "We examined the correlations between MYCN status, MYCN expression, and PHGDH expression in 94 samples with high-risk neuroblastoma, in the TARGET cohort; the expression of the genes in all samples was examined, that is, for cases with and without 11q LOH." (PMID 36319669, 2022). "Investigators have been able to decrease MYCN expression using antisense oligonucleotides and showed decreased neuroblastoma proliferation in vitro and tumor growth in vivo." (PMID 35454859, 2022). "Consistent with their higher sensitivity to ferroptosis, MYCN-amplified neuroblastoma cells had lower baseline GSH and cysteine levels compared to cell lines with lower MYC(N) activity scores." (PMID 35484422, 2022). "Treatment with cisplatin led to a significant increase in apoptosis of MYCN-amplified tumor cells, indicating a synergistic effect between cisplatin and miR-497 and therefore suggesting a potential neuroblastoma treatment." (PMID 35392988, 2022). "Analysis of three independent published studies demonstrated that miR-17-92 cluster expression in MYCN amplified neuroblastoma tissues was considerably higher than non-MYCN amplified neuroblastoma." (PMID 36793342, 2022). "Our study shows transsulfuration and GSH redox activity to be crucial to escape ferroptosis, whereas Gln import and glutaminolysis are required for ferroptosis in neuroblastoma cells with oncogenic MYCN." (PMID 35484422, 2022). "Treatment with BGA002 showed a marked reduction in all neuroblastoma cell lines, and combined treatment with RA further strengthened MYCN inhibition in a dose-dependent manner." (PMID 35490242, 2022). "In this context, blocking MYCN in MNA neuroblastoma leads to ROS production (through TRAP1 decrease), which the cancer cell fails to handle, consequently undergoing apoptosis." (PMID 36139583, 2022). "In particular, FOXD3-AS1 levels show a significant association with benign differentiation, International Neuroblastoma Staging System (INSS) stage, and MYCN amplification in neuroblastoma." (PMID 35280790, 2022). "MYCN-amplified neuroblastoma cells, like other MYC-driven cancer cells, have been found to be addicted to the amino acid glutamine (Gln), the absence of which causes growth arrest or apoptosis." (PMID 35484422, 2022). "It has been shown that MYCN stimulates the conversion of glutamine to glutamate in MYCN-amplified neuroblastoma cells by directly activating GLS2 transcription." (PMID 36077650, 2022). "With regard to MYCNOS, it has been reported to affect the growth of neuroblastoma cells by facilitating MYCN protein levels." (PMID 35832170, 2022). "Overexpression of GRP-R has been shown to enhance the stability of the oncoprotein N-myc, whereas knockdown of GRP-R destabilized N-myc in MYCN-amplified neuroblastoma cells." (PMID 36525420, 2022). "SCLC is sensitive to THZ1, a covalent CDK7 inhibitor with single-agent activity in T-cell acute lymphoblastic leukemia, MYCN- dependent neuroblastoma, and triple-negative breast cancer." (PMID 36163484, 2022). "Multi-omics profiling identified multiple cell type-specific and MYCN-regulated mechanisms inhibiting ferroptosis in adrenergic and mesenchymal neuroblastoma cells." (PMID 35484422, 2022). "We then used pharmacologic inhibitors to recapitulate our observation in MYCN-driven neuroblastoma Kelly and BE-2C cells." (PMID 35013218, 2022). "Most relevant here, up‐regulation of the SGOC pathway correlated with MYCN amplification in neuroblastoma, and MYCN sensitized neuroblastoma cells to pharmacological inhibition of one of its components, phosphoglycerate dehydrogenase." (PMID 36214609, 2022). "Combinations of E2F1 expression, E2F3 expression with MYCN amplification or age of diagnosis achieved better prognosis in neuroblastoma." (PMID 35764946, 2022).
neuroblastoma (continued). "Previous studies have reported radiomics potential role to predict molecular biomarkers in neuroblastoma, including MYCN in neuroblastoma by CT-based radiomics signature, tumor-associated macrophages by contrast-enhanced CT." (PMID 35204353, 2022). "Cumulatively, their data support a triple combination therapy by inhibiting GPX4, cystine uptake and cysteine synthesis to eliminate MYCN‐amplified neuroblastomas." (PMID 35908258, 2022). "For neuroblastoma generation, the expression of MYCN oncogene combined with the expression of ALK (anaplastic lymphoma kinase) was induced." (PMID 36142160, 2022). "The International Neuroblastoma Risk Group (INRG) classification system merges information including stage, age at onset, DNA ploidy, pathology, and MYCN status for prognosis." (PMID 36572864, 2022). "For instance, N-MYC proto-oncogene (MYCN), a particular deregulated oncogene of poor prognosis cancers, was primarily found in neuroblastoma samples ecDNAs." (PMID 35614494, 2022). "Here, we summarized and reviewed the recent research progresses for the critical function of BET proteins, as an epigenetic reader, on tumorigenesis and the therapeutic potential of the BET/BRD4 inhibitors on MYCN amplified neuroblastoma." (PMID 36187481, 2022). "Despite MYCN amplification being the first discovered genetic mechanism in neuroblastoma, its role in driving the pathology is not fully understood." (PMID 36139583, 2022). "We also determined the relationships of E2F3 expression, MYCN amplification and age of diagnosis in neuroblastoma patients." (PMID 35764946, 2022). "TARGET dataset had the oldest age of neuroblastoma diagnosis and the highest percentage of MYCN amplification." (PMID 35764946, 2022). "To further examine the SCNAs in neuroblastoma, we partitioned samples based on MYCN expression and found known patterns of SCNA co-occurrence." (PMID 35246212, 2022). "MYCN amplification is seen in approximately 20–25% of neuroblastoma cases and about 90% of the amplified tumors overexpress MYCN protein." (PMID 35053227, 2022). "Biopsy of a supraclavicular lymph node showed stroma poor, poorly differentiated, MYCN non‐amplified neuroblastoma (diagnosis sample in this study)." (PMID 36029175, 2022). "While the correlation between MYCN and its methylation status in neuroblastoma is still unclear, many other genes involved in neuroblastoma transformation were well characterized in both MYCN amplified and non-amplified tumors." (PMID 36139583, 2022). "Three of the molecular subgroups are strongly linked to clinical and genetic features that are known to be prognostic in neuroblastoma, with greater than 90% of groups 2, 3 and 4 exhibiting MYCN amplification, 11q deletion or infant diagnosis, respectively." (PMID 36175618, 2022). "A combination of untargeted metabolomics and targeted lipidomics reveals glycerolipid accumulation in MYCN-amplified neuroblastoma cell lines and primary tumors." (PMID 36077650, 2022). "The MYCN oncogene is a well-known driver of different, highly aggressive tumors (including Neuroblastoma, Small-Cell Lung Cancer, Rhabdomyosarcoma), where it is dysregulated and amplified and is strongly associated with poor survival prognosis." (PMID 35890348, 2022). "We have shown that treatment of MYC-driven neuroblastoma cells with CX-5461 and Halofuginone causes down-regulation of MYC and MYCN proteins and growth suppression MYC-driven neuroblastoma cell lines in vitro and preclinical models." (PMID 35053227, 2022). "The authors tested the therapeutic implication of their findings in vivo using an orthotopic MYCN‐driven neuroblastoma model." (PMID 35908258, 2022).
neuroblastoma (continued). "The overexpression of SMC2, in neuroblastoma with MYCN gene amplification, can also promote tumor growth by regulating DDR." (PMID 35992200, 2022). "Here, we describe the results of this testing conducted in two mouse cancer models, MMTV-HER2/Neu and Th-MYCN mice, that spontaneously develop breast cancer and neuroblastoma, respectively." (PMID 36449545, 2022). "In contrast to MYCN-overexpressing neuroblastoma, it is extremely rare to encounter gene amplification in the MYC-overexpressing neuroblastoma." (PMID 35053227, 2022). "MKI has been used to indirectly reflect the MYCN amplification, and it is independently prognostic in neuroblastoma." (PMID 35204353, 2022). "Increased TFR1 expression and decreased Fpn1 expression in MYCN-amplified neuroblastoma cells results in high intracellular iron content." (PMID 35530363, 2022). "In this study, by performing single amino acid deprivations in high MYCN and low MYCN neuroblastoma cells, we discovered strong dependency of high MYCN cells on the amino acid cysteine." (PMID 35484422, 2022). "Of the 15 patients with MYCN-NA neuroblastoma, 10 and 5 demonstrated complete and partial resolution of SMM respectively." (PMID 36686814, 2022). "Studies have found that MYCN oncogene is an extremely high-level amplification observed in approximately 20% of neuroblastoma cases." (PMID 36438198, 2022). "CBS, AHCY and PHGDH expression was also elevated in mass spectrometry-based global proteomes from MYCN-amplified neuroblastoma tumors." (PMID 35484422, 2022). "We therefore studied the impact of verlindamycin on neuroblastoma cells to show that this compound decreases proliferation rate and MYCN expression, whereas enhances cell differentiation in combination with ATRA." (PMID 34522028, 2022). "We employed our syngeneic SK-N-SH neuroblastoma cell pair expressing exogenous MYCN or GFP and performed untargeted liquid chromatography/tandem mass spectrometry of cell lysates to determine changes in a broad array of polar metabolites." (PMID 35174317, 2022). "SLC27A2-mediated fatty acid uptake is crucial for the survival of MYCN-amplified neuroblastoma cells." (PMID 36077650, 2022). "Age at diagnosis and MYCN amplification are critical determinants of the clinical outcomes of paediatric neuroblastoma." (PMID 35655142, 2022). "The TH-MYCN model is a model of spontaneous and aggressive neuroblastoma that is also driven by MYCN overexpression." (PMID 35943801, 2022). "As a result, MYCN overexpression significantly increases intracellular pools of nucleotides in neuroblastoma cells." (PMID 36077650, 2022). "Several molecular and cytogenetic factors related to the prognosis of neuroblastoma have been proposed, including MYCN amplification, DNA content (ploidy), and changes in chromosome structure." (PMID 36237324, 2022). "We recently demonstrated that inducing ferroptosis genetically or pharmacologically in MYCN-amplified neuroblastoma (NB) is a novel and effective way to kill these cells." (PMID 35174317, 2022). "Amplification of the protooncogene MYCN and subsequent overexpression of the oncoprotein N-Myc occurs in approximately 25% of neuroblastomas and correlates with poor outcomes." (PMID 36445966, 2022). "EZH2 is highly expressed in MYCN-amplified neuroblastoma, maintaining the tumor cells in an undifferentiated state, and EZH2 inhibition reduces neuroblastoma growth in vitro and in vivo." (PMID 35681734, 2022).
neuroblastoma (continued). "As different studies have highlighted, MYCN amplification reshapes the neuroblastoma landscape by creating undifferentiated, aggressive, highly vascularized, disseminating, and nearly untreatable tumors." (PMID 35490242, 2022). "The efficiency of MYCMI-7 toward MYCN-amplified neuroblastoma cells was even stronger in three-dimensional (3D) cultures, with GI50 in the nanomolar range." (PMID 36874405, 2022). "MYCN was originally identified as an amplified gene, homologous to the myelocytomatosis viral oncogene v-myc, in neuroblastoma cell lines." (PMID 36077650, 2022). "For this purpose, we used ecDNA from human neuroblastoma cells, Kelly, to map and recover the entire 966 kb extrachromosomal MYCN oncogene amplicon." (PMID 35711922, 2022). "Based on the expression levels of E2F1 and MYCN amplification, pediatric neuroblastoma patients were divided into four sub-groups." (PMID 35764946, 2022). "MYCN-amplified neuroblastoma has been identified as particularly sensitive to ABT-199 treatment, and, in xenograft models, ABT-199 induced apoptosis and tumour regression in combination with the Aurora-A inhibitor MLN8237." (PMID 35568716, 2022). "Our results indicate that 11q-deleted neuroblastoma and MYCN amplified neuroblastoma coalesce by downregulating miR-548l." (PMID 36396668, 2022). "The expression level of MYCN correlates with the prognosis of neuroblastoma, and overexpression of human MYCN gene produces neuroblastoma in mice." (PMID 34625907, 2022). "Molecular testing of the tumor has become important for overall prognosis, and MYCN gene amplification is an important marker for poor prognosis and aggressive disease in neuroblastoma." (PMID 36360435, 2022). "B cells significantly migrated toward three of four neuroblastoma cell lines supernatants, independently of MYCN amplification status." (PMID 36923280, 2022). "Studies found that 25% of patients with neuroblastoma showed an MYCN amplification and predicted poor prognosis independently of other factors." (PMID 35957699, 2022). "The longevity and motility of MYCN-amplified neuroblastoma cells are impaired by ectopic delivery of miR-186 to NK cells and neuroblastoma cells, and TGF-dependent suppression of NK cytotoxicity is averted." (PMID 36338993, 2022). "Taken together, our study uncovered mechanisms crucial to ferroptosis escape in MYCN-amplified neuroblastomas; simultaneous inhibition of those mechanisms led to tumor regression in vivo." (PMID 35484422, 2022). "Biopsy of the primary tumor showed stroma poor, MYCN amplified neuroblastoma (diagnosis sample in this study)." (PMID 36029175, 2022). "The differential efficacy of EZH2 inhibitors in neuroblastoma tumor cell lines prompted us to further evaluate Ezh2 regulation of MYCN in mice." (PMID 35013218, 2022). "SMAD9 forms a positive transcriptional feedback loop with MYCN and represents a unique tumor dependency for MYCN-amplified neuroblastoma." (PMID 36539767, 2022). "There are two main aspects to the mechanism: 1) local enhancer-induced MYCN amplification in neuroblastoma ecDNA." (PMID 35844796, 2022). "Treatment with MYCMI-7 reduced tumor growth and viability in all the neuroblastoma cell lines, but the effect was significantly stronger in the MYCN-amplified cases." (PMID 36874405, 2022). "Collectively, these findings identify cysteine addiction as a new liability in MYCN‐amplified neuroblastomas and propose to use ferroptosis‐inducing therapeutic strategies to treat MYCN‐driven neuroblastomas." (PMID 35908258, 2022). "MYCN-amplified neuroblastomas have also been reported to contain less CD4 + and CD8 + T cells, dendritic cells, NK cells, and macrophages compared to non-MYCN-amplified neuroblastomas." (PMID 35362827, 2022). "MYCN amplification results in the downregulation of CCL2 in neuroblastoma cells, which seems involved in NK and T cells infiltration." (PMID 36923280, 2022).
neuroblastoma (continued). "Altogether, these results support that Ezh2 is indispensable for sustaining MYCN deregulation and maintaining MYCN-driven neuroblastoma in vivo." (PMID 35013218, 2022). "The third sample, the zPDX from the neuroblastoma culture with MYCN amplification and PIK3CA (phosphatidylinositol-4,5-bisphosphate 3-kinase catalytic subunit alpha) mutation, responded only moderately to the ALK inhibitor ceritinib out of five tested drugs." (PMID 35159116, 2022). "Antigene therapy by targeting MYCN transcription has great potential in treating MYCN-expressing tumors, as was previously demonstrated in the preclinical treatment of neuroblastoma and rhabdomyosarcoma by MYCN-specific agPNA." (PMID 35890348, 2022). "We also used the neuroblastoma Tet21 model in which MYCN expression is doxycycline-inducible (Tet-off)." (PMID 35296644, 2022). "In summary, our data show that GPX4 partially protects high MYCN neuroblastoma cells from ferroptosis in vitro and in an orthotopic neuroblastoma mouse model." (PMID 35484422, 2022). "Antigene oligonucleotide therapy by targeting MYCN transcription has been demonstrated by the novel MYCN-specific agPNA BGA002 in the preclinical treatment of neuroblastoma, and has also great potential in treating other aggressive MYCN-expressing tumors." (PMID 36139583, 2022). "Age of neuroblastoma diagnosis, percentage of MYCN amplified neuroblastoma and platforms of the four datasets were significantly different." (PMID 35764946, 2022). "Chemotherapy resistance of neuroblastomas with amplified MYCN was related with Cat D expression, and they suggest that enhancement of Bcl-2 anti-apoptotic function." (PMID 35715412, 2022). "Except MYCN amplification and age of diagnosis, more reliable prognostic markers are required to predict the clinical outcomes of neuroblastoma." (PMID 35764946, 2022). "Based on this method, a knockout of gas7 promoting neuroblastoma metastasis in transgenic fish overexpressing MYCN was obtained." (PMID 36142160, 2022). "MYCN is a key driver of the disease and its overexpression reprograms neuroblastoma cells towards a stem-like phenotype that affects proliferation and cell growth, metabolism, and apoptosis inhibition." (PMID 35490242, 2022). "For this reason, high levels of MYCNOS can be found relative to MYCN over-expression and correlate with poor outcome in neuroblastoma." (PMID 36139583, 2022). "To evaluate the immunogenic changes occurring upon treatment with PBNP-PTT at varied thermal doses across neuroblastoma cell lines with different MYCN amplification statuses, we compared the effects of thermal dose on SH-SY5Y cells versus LAN-1 cells." (PMID 35326601, 2022). "The aim of our study was to analyze the link between neuroblastoma risk factors and prognosis in pediatric patients and to see if there is an association between IDRF and other prognostic factors such as age, MYCN status, NSE value and tumor size." (PMID 36360435, 2022). "A recent study also reported that MYCN transcriptionally upregulates the system Xc− transporter to meet the increased demand of MYCN-amplified neuroblastoma cells to detoxify ROS by glutathione." (PMID 36077650, 2022). "Taken together, this study established the novel EV-based method for detecting MYCN status in pediatric neuroblastoma." (PMID 35681607, 2022). "Taken together, these data suggest that EZH2 depletion induces MYC(N) degradation not only in neuroblastoma cells but also in other cancer cells overexpressing either the MYCN or MYC oncogene." (PMID 35013218, 2022). "TERT expression has been suggested to be a key molecular feature in neuroblastoma, and increased TERT expression has been associated with MYCN amplification." (PMID 36175618, 2022). "In young infants, neuroblastic tumors (neuroblastomas or ganglioneuroblastomas) have favorable biological characteristics and rarely MYCN amplification (an unfavorable feature)." (PMID 36011005, 2022).